STAT1 (signal transducer and activator of transcription 1)
Diseases named in the same sentence as STAT1 in open-access papers (continued):
Sharing a sentence is not in itself a finding about the gene and the disease.
cancer (continued). "In addition, STAT1/3/5 has been shown to influence ERα in cancer and other diseases and the ISG, IFI27, can directly downregulate ERα expression." (PMID 34680281, 2021). "In the majority of trials, high expression of STAT1 leads to improved clinical outcomes, but contradictive data has been shown suggesting that the clinical findings of cancer patients with high expression of STAT1 and/or pSTAT1 are poorer as contrasted with low expression patients." (PMID 33986802, 2021). "The epigenetic activation of the STAT1 gene may be a universal event in various types of cancers, especially in the IFN-resistance of cancer cells or individuals with a poor response to alisertib." (PMID 34522170, 2021). "Although VAV2 inhibitor is currently unavailable, the STAT1 signaling pathway is druggable and may serve as an alternative target for reversing radioresistance of cancer cells." (PMID 34462423, 2021). "For example, LCK activity could improve T-cell responses in cancer immunotherapy, and STAT1 expression was demonstrated as a potential biomarker for anti-PD-1/anti-PD-L1 for cancer patients." (PMID 34603338, 2021). "The expression and activity of STAT1 is misregulated in cancer." (PMID 34572789, 2021). "To investigate whether expression of STAT1 was also upregulated after a short exposure of the cancer cells to alisertib, we evaluated the time course and found that the levels of STAT1 were obviously induced as early as at 48 h." (PMID 34522170, 2021). "IFN-γ enables to induce cancer cell dormancy through the activation of STAT1." (PMID 33771156, 2021). "While STAT1 and STAT2 primarily drive immune signalling initiated by interferons, STAT3 and STAT5 have widely been linked to the survival and proliferative potential of a number of cancers." (PMID 32899142, 2020). "Considering cancer stem cells are deemed to drive the progression and relapse of cancer, these data may support the perspective that STAT1 is a inhibit factor of stemness." (PMID 32516753, 2020). "Also three-dimensional imaging and FACS analyses revealed that the adoptively transferred T cells and dendritic cells infiltrated RT2-cancers of Stat1−/− or Stat1+/+ mice with similar dynamics; immune histology confirmed these findings." (PMID 32165639, 2020). "Patients with Stat1high or Ido1high cancers showed a trend towards improved survival 50 months after diagnosis, which might reflect beneficial effects of Stat1 in stromal immune cell activation." (PMID 32444775, 2020). "Therefore, it is generally considered that Stat1 expression and activation in immune cells and in cancer cells suppresses tumorigenesis." (PMID 32444775, 2020). "Previously, many experiments showed that STAT1 may transcriptionally activate PD-L1 in various types of cancers and mediated the inactivation of T cells." (PMID 32891166, 2020). "We also found increased phosphorylated Stat1 by ATO treatment in ESCC cancer cells." (PMID 33046973, 2020). "Moreover, Notch3 triggered by stromal cell-derived exosomes activated antiviral signaling depending on STAT1 in cancer cells." (PMID 32028262, 2020). "Furthermore, we show that downstream signaling through STAT1 that drives cancer stemness is dependent on STAT2, but is inhibited by STAT3." (PMID 31992798, 2020). "The Stat1-positive RT2-cancers became growth arrested or regressed." (PMID 32165639, 2020). "The activation of IFNAR1/2 in turn activates STAT1 and ISGs driving cancer stemness." (PMID 31992798, 2020). "In addition, interactions between HIF-1 and IRF-1, and HIF-1 and STAT1 have also been reported in mice, and these regulate the expression of iNOS and induce apoptosis in cancer cells." (PMID 31937813, 2020). "STAT1 has been reported to play numerous roles in cancer biology." (PMID 32275681, 2020). "Interestingly, IFN-γ is an important inducer of PD-L1 expression, which acts via the JAK/STAT1/interferon regulatory factor (IRF) in various types of cancers, including NSCLC." (PMID 32252414, 2020).
cancer (continued). "Therefore, p-STAT1 and u-STAT1 were thought to have distinct functions and have been used as independent prognostic markers in predicting disease outcomes in cancer." (PMID 30456450, 2019). "However, the expression of p-STAT1 was reduced in the E18-14C-27 cancer cells treated with rexinoids." (PMID 31700995, 2019). "In addition, expression of STAT1 has been found to correlate with both good and poor prognosis in different types of cancers." (PMID 30456450, 2019). "In some malignant phenotypes, STAT1 could carry out its functions either as an oncoprotein or cancer suppressor in the same cell type, depending on the specific genetic background." (PMID 31438997, 2019). "STAT1 is deeply involved in the antiviral response triggered by endogenously produced Interferons but also in the therapeutic responses to exogenously administered Interferons in cancer treatments and anti-viral therapies." (PMID 31752278, 2019). "Deregulated expression of STAT1 has been observed in a variety of cancer types." (PMID 30456450, 2019). "The oncogenic role of STAT1 in certain types of cancer including HNSCC has been described." (PMID 30847302, 2019). "IFN-γ mainly produced by effector T cells and NK cells could be involved in cancer dormancy via STAT1 signaling." (PMID 31297335, 2019). "Additionally, IL-12, IL-27, IL-17 and TNF-α regulated PD-L1 expression in inflammatory cells and cancer cells by altering NF-κB, STAT1 and ERK1/2 signaling." (PMID 29690901, 2018). "As STAT1 is upregulated in carcinoma tissue (FC 1.55), it could be that these mRNAs are upregulated as a result of increased STAT activity." (PMID 30603058, 2018). "IFN-γ-induced apoptosis is mediated by STAT-1 signaling in a variety of cancer cells." (PMID 29278364, 2017). "Mechanistically, MBZ can modulate several cancer-associated pathways, such as ELK1/SRF, AP1, STAT1/2, MYC/MAX, although the regulatory outcomes may be context-dependent." (PMID 28099902, 2017). "Furthermore, an abnormal STAT1 activation and a specific IFN-related gene signature has been linked to chemo-resistance and poor prognosis in cancer patients." (PMID 28636670, 2017). "Therefore, we developed a method to measure the nitration of STAT1 within PBMC collected from cancer patients." (PMID 29133913, 2017). "IFNγ has been shown to stimulate PD‐L1 expression downstream of Stat1 in several cancer cells." (PMID 27932443, 2017). "TEAD-AP1 cooperation with steroid receptor coactivators (SRC) drives downstream gene transcription to regulate cancer cell migration and invasion, and STAT1, STAT2 and IRF9 form a heterotrimer that regulates transcription of genes containing IFN-stimulated response elements." (PMID 27899659, 2017). "However, accumulating evidence has shown that the ERK was aberrantly expressed in cancers and correlated with STAT1 depression." (PMID 28431406, 2017). "In order to measure nitrated STAT1, we developed a novel mass spectrometry technique to detect whether elevated levels of nitrated STAT1 would be found in the immune cells of cancer patients." (PMID 29133913, 2017). "The exact role of CDK8 in the process of immune-evasion of cancer cells is still unknown, however it may be partially related to the STAT1 S727 dependent repression of NK-cells cytotoxicity." (PMID 28422713, 2017). "Furthermore, the responses to chemotherapy were tightly related to the activation of IFN/STAT1 signaling in post-treatment residual cancer cells." (PMID 27791205, 2016). "Since STAT1 has been shown to promote apoptosis and carry tumor suppressor functions in different types of cancers, the correlation among parameters we reported here will help to explain the mechanism of our developed interferon alpha 2b in the cancer treatment." (PMID 27110503, 2016). "Since persistent STAT activation often occurs in cancer, we were interested whether the oncogenic activation of PDGFRα also leads to the activation of STAT1, STAT3 and STAT5 transcription factors." (PMID 25880691, 2015).
cancer (continued). "PGE-2 has been shown to interfere with STAT1 activity, and may therefore contribute to the incapability of CAFs to activate STAT1 signaling in cancer cells." (PMID 25853091, 2015). "In addition, the rest of TFs such as PPARG, PPARA, SMAD3, MYC, and STAT1 have been proved to be related to cancer progression." (PMID 26425543, 2015). "Interestingly, although fludarabine reportedly inhibits STAT1 phosphorylation in normal and cancer cells, the signaling cascade leading to IDO expression remained unaltered in our system." (PMID 24911872, 2014). "Activation of signal transducer and activator of transcription 1 (STAT1) in cancer cells by the increased interferon gamma (IFN-γ) production in immune cells played an important role in downregulating HER2 in cancer cells upon engagement of immune cells by trastuzumab." (PMID 24693969, 2014). "STAT1 overexpression has been demonstrated in several types of human cancer." (PMID 25355139, 2014). "Nevertheless, in some cancers STAT1 can act in an anti-apoptotic manner." (PMID 24810717, 2014). "Additionally, in cancer cells, miR-145 is reported to target Stat1, the main signal transducer of the IFN-γ pathway, in addition to c-Myc." (PMID 24800866, 2014). "Previous studies have demonstrated that STAT1 is overexpressed in several human cancers." (PMID 23365759, 2013). "Interestingly, the sensitivity of model variables is robust against parameter variations and against differences between IFNγ induced STAT1 signalling in pancreatic stellate and cancer cells." (PMID 23284277, 2012). "Perturbation of the STAT1/3 balance induced by the different timing regimens of TLR4/9 agonist complex application directed cytokine/growth factor signals from apoptotic to proliferative or from cancer immunosurveillance to cancer immunoediting." (PMID 21931823, 2011). "Dysfunctional STAT1 may contribute to cancer development and progression, while at the same time the ERK1/2 pathway regulates a common set of cell death regulators such as BCL-2, BCL-XL and BIM, indicating that it plays a role in cell cycle control." (PMID 21625390, 2011). "Thus, it is possible that activation of the IFN-γ/STAT-1/IRF-1 pathways serves to counteract the constitutive activation of STAT-3 in some cancer cell lines in the context of metastatic melanoma." (PMID 21875439, 2011). "For instance, STAT1 is becoming increasingly important in cancer biology." (PMID 21182795, 2010). "There has been an established link between Stat1 phosphorylation and human cancer." (PMID 18941537, 2008). "Since biological effects of IFN-α and IFN-γ are both mediated by Jak1, it appeared that Tyk2 tyrosine kinase or the receptor may be impaired in IFN-α resistant carcinoma cells upstream of STAT1." (PMID 11875714, 2002). "The upregulation of interferon-related genes (Stat1, Irf1) suggests activation of antitumor immune responses, while downregulation of metabolic enzymes like Enox1 may indicate metabolic reprogramming of cancer cells." (PMID 40969227, 2025). "In addition, treatment with PYR41, a ubiquitin-activating enzyme E1 inhibitor, and MLN4924, an E3 ligase inhibitor, did not decrease total levels of p-STAT1/2, but markedly reduced the cytosolic p-STAT2 puncta as well as p-STAT1/2 levels in LEVs from USP5-depleted cancer cells." (PMID 41321309, 2025). "Thus, it is possible that casein family members could be used as novel biological molecules for cancer treatment by the activation of interferon signaling via upregulation and hyperactivation of STAT1." (PMID 38990440, 2024). "However, recently study has unearthed an oncogenic potential for STAT1 in certain cancers." (PMID 38750462, 2024). "Additionally, the distribution of STAT1, STAT2, STAT3, STAT4, STAT5A, STAT5B, and STAT6 expression in CD4+ T cells in pan-cancer were also clearly illustrated, which showed that STAT1 and STAT2 expression were notably up-regulated in CD4+ Treg cell with marker OSA1 and CD4+ T cell with ISG IFIT1." (PMID 36968603, 2023).
cancer (continued). "Overall, this pathway seems to be of interest in cancer treatment, as it has been shown that patients of several cancer types, such as lung and prostate cancers, have a worse outcome when STAT3 and 5 are activated, while STAT1 activation is generally associated with better prognosis." (PMID 36769210, 2023). "Thus, therapeutic approaches that specifically downregulate STAT3 transcriptional activity and/or upregulate STAT1 transcriptional activity may be promising in cancer treatment." (PMID 38022653, 2023). "Indeed, STAT1 is known to upregulate expression of MHC class I, and therefore, alleviation of STAT1 signaling might well explain decreased MHC class I antigen presentation in CIN+ cancers." (PMID 37561163, 2023). "However, we found a number of established drivers of cancer progression and invasion (e.g., mTOR, STAT1/5, RHOC, ARF6, HMGB, and CRK) with increased expression levels as well as known suppressors (e.g., AIFL1 and SLIT3) with decreased expression levels upon PTEN inhibition." (PMID 36555834, 2022). "However, aberrant STAT1 activation has been found in several types of human cancer." (PMID 35313878, 2022). "Moreover, STAT1 exerts a regulatory effect on the radiosensitivity of a variety of cancer cells." (PMID 36061358, 2022). "The unphosphorylated state of TF STAT1 enduring upregulation is responsible for the promotion of cancer growth and metastasis, and the deterioration of the immune response, leading to drug resistance and forcing cancer cells to invade and migrate to other organs in advanced PCa." (PMID 35164166, 2022). "Therefore, STAT1 downregulation attenuated the anti-cancer effects induced by 125I and EPI in vivo." (PMID 35692770, 2022). "Previous reports suggest that STAT2, like STAT1, may play a dual role in cancer progression." (PMID 36061181, 2022). "The findings of our study confirm our hypothesis that EPI can promote the anti-cancer effects of 125I seed implantation on HCC cells via the JAK/STAT1 pathway by enhancement of HCC cell apoptosis, inhibition of cell proliferation and migration, and arrest of the cell cycle at the G2/M phase." (PMID 35692770, 2022). "Therefore, STAT1 might play an important role in the differences in the immune conditions of cancer tissues." (PMID 33608980, 2021). "Similarly, abundant studies demonstrated that E2F4, STAT1, MYC, ERG, and NFYB may play an important role in the pathogenesis and progression of various cancers, including OSCC, and the underlying mechanism may be related to dysregulated lncRNA." (PMID 32923393, 2020). "Hence, we examined the effect of poly‐G ODN on the JAK/STAT1 pathway activated by IFN‐α or IFN‐β using western blotting and flow cytometry to exclude the possibility of direct inhibition of JAK/STAT1 phosphorylation in cancer cells, and clearly determine the specificity of ODN to IFN‐γ." (PMID 32067413, 2020). "Following ICB Stat1-deficient cancers showed neither increased p16Ink4a nor p21Cip1." (PMID 32165639, 2020). "Notably, it seems that STAT1 is considered as a pro-tumorigenic pathway, so that several studies have revealed that the STAT1 signaling pathway significantly enhances the proliferation and malignancy of cancer cells." (PMID 31569687, 2019). "Therefore, further understanding of the molecular mechanism by which STAT1 down-regulates hypoxia-induced transcription may also lead to the development of a better therapeutic measure for cancer treatment." (PMID 27769057, 2016). "Targeting of STAT1 might be a potential strategy to sensitize cancer cells." (PMID 25705130, 2015). "However, recent studies identified STAT1 as a proto-oncogene product in a variety of cancers." (PMID 26654227, 2015). "For Panobinostat, a pan-HDAC inhibitor that has been hypothesized to act on cancer cells through a number of diverse mechanisms, we identified the up-regulation of STAT-1/interferon signaling as a principal factor of inherent resistance across multiple cancer lineages." (PMID 25036042, 2014).
cancer (continued). "Thus, the physiological role of STAT1 during cancer development remains poorly understood and may be context-dependent." (PMID 22264274, 2012). "The results revealed that key transcription factors of the IFN-γ signalling pathway, including STAT1 and IFR1, exhibited increased activity in MHC-II+ cancer cells." (PMID 41281745, 2025). "Finally, dysregulation of histone acetylation has been shown to directly influence the pro-inflammatory cancer microenvironment through hyperacetylation of pro-inflammatory transcription factors such as signal transducer and activator of transcription 1 and 3 (STAT1/3) and NF-κB." (PMID 39796780, 2025). "The results revealed that the overexpression of STAT1 or IRF9 alone inhibited the stemness of cancer cells and that the co-overexpression of STAT1 and IRF9 strongly suppressed cancer stemness." (PMID 39781458, 2025). "Specifically, we revealed that FAT1 can phosphorylate CaMKII and further impede the formation of the p-STAT1/IRF9 complex, thereby exerting its role in suppressing cancer." (PMID 39781458, 2025). "STAT1 expression was present in all gene hubs, with particular emphasis on the fourth, which represents the transition from HSIL to invasive cancer." (PMID 41367865, 2025). "Similar to STAT1, several key proteins have been identified that regulate MHC transcription at the transcriptional level, influencing cancer immunotherapy outcomes." (PMID 40673641, 2025). "We identified their distinct functions in cancer persistence and found that PRMT1 is the essential isoform in the type I PRMT family to target for reducing STAT1-promoted persistence." (PMID 39699269, 2025). "In conclusion, our results showed that STAT1 and UCP2 are upregulated in cervical precursor lesions as they progress to cancer." (PMID 41367865, 2025). "Various key proteins have been identified as regulators of STAT1, modulating MHC expression at the transcriptional level and thereby influencing the efficacy of cancer immunotherapy." (PMID 40673641, 2025). "In summary, the data confirm that STAT1 and STAT3 have opposing roles in the cancer biology of NHLs." (PMID 40287766, 2025). "HSP90AA1 aids antigen release from cancer cells in TIME, while EZH2, STAT1, and ICAM1 hinder immune cell infiltration." (PMID 40352921, 2025). "JAK1, STAT1, and STAT3 expressions were stronger in PROC than in the platinum-sensitive group of primary chemotherapy-naive cancer tissues." (PMID 40883550, 2025). "STAT1 (Signal Transducer and Activator of Transcription 1) and UCP2 (Uncoupling Protein 2), known for their roles in other cancers, were selected for further validation." (PMID 41367865, 2025). "In cancer cells, MUC1-C drives auto-inductive chronic inflammatory signaling involving STAT1-mediated regulation of STING and downstream ISGs that amplify the type I and II IFN pathways." (PMID 40781226, 2025). "Monocyte derivatives control tissue microenvironments in tumors and in chronic inflammatory diseases and inhibitors of monocyte signaling have been applied in cancer and in PAH where STAT1 inhibition is effective in preventing PAH." (PMID 40234964, 2025). "Among the seven different STAT proteins identified in mammals, STAT1 and STAT3 are the most intensely studied family members given their prominent and partially antagonistic roles in immune reactions and cancer development." (PMID 40287766, 2025). "We found that TAK-981-induced MYC downregulation promoted the activation of STING followed by Stat1 and MHC class I in KRAS-mutant cancer cells." (PMID 39334463, 2024). "Our investigation additionally reveals that STAT1 plays a role in the transcriptional regulation of HK2, further delineating the complex network of molecular interactions driving cancer metabolism." (PMID 38750462, 2024).